PLK3 (polo like kinase 3)
Description:
Serine/threonine-protein kinase involved in cell cycle regulation, response to stress and Golgi disassembly. Polo-like kinases act by binding and phosphorylating proteins that are already phosphorylated on a specific motif recognized by the POLO box domains. Involved in cell cycle regulation: required for entry into S phase and cytokinesis. Phosphorylates BCL2L1, leading to regulate the G2 checkpoint and progression to cytokinesis during mitosis. Plays a key role in response to stress: rapidly activated upon stress stimulation, such as ionizing radiation, reactive oxygen species (ROS), hyperosmotic stress, UV irradiation and hypoxia. Phosphorylates CHEK2 in response to DNA damage, promoting the G2/M transition checkpoint. Phosphorylates the transcription factor p73/TP73 in response to DNA damage, leading to inhibit p73/TP73-mediated transcriptional activation and pro-apoptotic functions. Phosphorylates HIF1A and JUN is response to hypoxia. Phosphorylates ATF2 following hyperosmotic stress in corneal epithelium. Also involved in Golgi disassembly during the cell cycle: part of a MEK1/MAP2K1-dependent pathway that induces Golgi fragmentation during mitosis by mediating phosphorylation of VRK1. May participate in endomitotic cell cycle, a form of mitosis in which both karyokinesis and cytokinesis are interrupted and is a hallmark of megakaryocyte differentiation, via its interaction with CIB1.
Synonyms: PLK-3; CNK; FNK; PRK
Tractability: Small molecule: a structure with a bound ligand is known; a high-quality ligand is known; it belongs to a druggable protein family. PROTAC: a small molecule that binds it is known.
Target class: Other protein kinase PLK family; Kinase; Enzyme; Protein Kinase; Other protein kinase group
Chemical probes: BI 2536 (high quality), PD081795
Gene: Protein-coding gene on chromosome 1 (44,800,346 to 44,805,995, forward strand). Ensembl gene ENSG00000173846.
Subcellular location: Cytoplasm; Nucleus; Nucleus, nucleolus; Golgi apparatus; Cytoplasm, cytoskeleton, microtubule organizing center, centrosome
Pathways (Reactome):
Cell Cycle: Ubiquitin-Mediated Degradation of Phosphorylated Cdc25A
Gene Ontology:
Molecular function: protein binding; protein serine/threonine kinase activity; ATP binding; protein kinase activity; protein serine kinase activity
Biological process: cytoplasmic microtubule organization; DNA damage response; G1/S transition of mitotic cell cycle; Golgi disassembly; negative regulation of apoptotic process; negative regulation of transcription by RNA polymerase II; positive regulation of chaperone-mediated autophagy; positive regulation of intracellular protein transport; positive regulation of proteasomal ubiquitin-dependent protein catabolic process; regulation of cell division; regulation of cytokinesis; response to osmotic stress; response to radiation; response to reactive oxygen species; apoptotic process; endomitotic cell cycle; G2/M transition of mitotic cell cycle; mitotic G1/S transition checkpoint signaling; mitotic spindle organization; negative regulation of phosphatidylinositol 3-kinase/protein kinase B signal transduction; protein phosphorylation; positive regulation of autophagy; positive regulation of protein catabolic process; and 3 more
Cellular component: centrosome; cytoplasm; Golgi stack; nucleolus; nucleus; kinetochore; nucleoplasm; spindle pole; dendrite; Golgi apparatus; neuronal cell body
Genetic constraint (gnomAD): Loss-of-function variants: 40 observed, 67.94 expected, observed/expected ratio (o/e) 0.59, 90% interval 0.46 to 0.77. The upper end of that interval is the gene's LOEUF score, 0.77, which puts it in group 3 of 6, group 1 being the genes least tolerant of losing a copy. Missense variants: 782 observed, 853.69 expected, observed/expected ratio (o/e) 0.92, 90% interval 0.86 to 0.97. Synonymous variants: 364 observed, 346.65 expected, observed/expected ratio (o/e) 1.05, 90% interval 0.96 to 1.14.
Homologues: Orthologues: chimpanzee PLK3 (99% identical), macaque PLK3 (97% identical), rabbit PLK3 (96% identical), rat Plk3 (94% identical), mouse Plk3 (93% identical), pig PLK3 (92% identical), dog PLK3 (92% identical), guinea pig PLK3 (91% identical), tropical clawed frog plk3 (62% identical), zebrafish plk3 (57% identical). Paralogues in human: PLK2 (50% identical), PLK1 (38% identical), PLK4 (25% identical), PLK5 (19% identical).
Diseases named in the same sentence as PLK3 in open-access papers:
PLK3 is named in the same sentence as 56 diseases in open-access papers, as found by Europe PMC text mining. Sharing a sentence is not in itself a finding about the gene and the disease. The quoted sentences say what the papers report.
colorectal cancer (7 papers, 2013 to 2021). A primary or metastatic malignant neoplasm that affects the colon or rectum. "Some results from in vitro and in vivo studies showed that PLK3 inhibited the growth of colorectal cancer." (PMID 34080290, 2021). "In colorectal cancer, PLK3 inhibits glucose metabolism by targeting HSP90/STAT3/HK2 signal transduction." (PMID 34217310, 2021). "This study suggests that PLK3 inhibits glucose metabolism by targeting HSP90/STAT3/HK2 signaling and PLK3 may serve as a potential therapeutic target in colorectal cancer." (PMID 31655629, 2019). "However, the role of PLK3 in colorectal cancer (CRC) progression and glucose metabolism remains to be known." (PMID 31655629, 2019). "For instance, Polo‐like kinase 3 (PLK3) could inhibit glucose metabolism by targeting HSP90/STAT3/HK2 signalling, indicating it may serve as a potential therapeutic target in colorectal cancer." (PMID 34423480, 2021). "Whether the combination of selenium and sulindac can target on Plk3-HIF-1α-PTEN signaling, for colorectal cancer prevention and therapy, is under investigation." (PMID 23327547, 2013).
gastric cancer (7 papers, 2015 to 2021). A primary or metastatic malignant neoplasm involving the stomach. "Although several studies have demonstrated that HOXA-AS2 promotes tumor proliferation by serving as an “miRNA sponge”, it has also been shown to enhance gastric cancer proliferation by epigenetically silencing the expression of p21, plk3, and DDIT3." (PMID 34511122, 2021). "In gastric cancer, the expression of P21, PLK3, and DDZT3 is inhibited by binding of HOXA-AS2 to EZH2, which promotes tumor proliferation and inhibits tumor cell apoptosis." (PMID 32760226, 2020). "lncRNA HOXA-AS2 promotes gastric cancer proliferation by epigenetically silencing P21/PLK3/DDIT3 expression." (PMID 28881797, 2017). "Long non-coding RNA HOXA-AS2 promotes gastric cancer proliferation by epigenetically silencing P21/PLK3/DDIT3 expression by binding with EZH2 (enhaner of zeste homolog 2)." (PMID 29221147, 2017).
prostate carcinoma (7 papers, 2015 to 2024). A carcinoma that arises from epithelial cells of the prostate gland. "An increase in ALDH1A1 in prostate cancer bone metastases was associated with high PLK3 expression." (PMID 38928275, 2024). "ALDH1A1 gain in prostate cancer bone metastases is associated with high PLK3 expression." (PMID 38169509, 2024). "Additionally, the study revealed that ALDH1A1 overexpression is associated with high expression of Polo-like kinase 3 (PLK3) in prostate cancer bone metastases, suggesting that ALDH1A1 regulates PLK3 through its interplay with AR and RAR-dependent transcription." (PMID 39796106, 2024). "PLK3 contributes to the control of prostate cancer cell proliferation, migration, DNA repair, and radioresistance." (PMID 38169509, 2024). "PLK3 is involved in controlling prostate cancer cell proliferation, migration, DNA repair, and radio-resistance." (PMID 38928275, 2024). "ALDH1A1-based regulation of PLK3 enhances cellular proliferation and migration, driving tumor progression and metastasis in prostate cancer." (PMID 39796106, 2024). "In human cells, PLK3 has garnered interest for its possible effect on the treatment response in colon carcinoma, prostate cancer, and melanoma." (PMID 38630692, 2024). "The results demonstrated that ALDH1A1 and PLK3 may serve as biomarkers to predict metastasis and the development of radio-resistance in prostate cancer patients and may represent potential therapeutic targets to eliminate metastatic cells." (PMID 38928275, 2024). "Finally, there is emerging evidence that expression of PLK3 could affect the therapeutical response in melanoma, prostate cancer and colon carcinoma." (PMID 32575753, 2020).
colon carcinoma (6 papers, 2004 to 2024). "For PLK isoenzymes other than PLK1 only sparse information on expression in various tumour entities is available, with only one study in mice reporting a relative loss of expression for PLK3 mRNA in colon carcinomas in comparison to adjacent normal colon mucosa." (PMID 14970859, 2004). "The gene expression signature of Plk3 has shown deregulated expression of Plk3 in various types of cancers, such as head and neck squamous cell carcinomas and colon cancer." (PMID 22852086, 2012). "Reduced mRNA levels of PLK3 in many types of cancer has been reported, including lung cancer, head and neck cancer, and colon cancer, suggesting that reduced Plk3 expression may contribute to tumor development." (PMID 23210979, 2012). "However, the PLK3 expression level appears to be downregulated in induced colon tumors, as well as in bladder, uterus, and head and neck tumors, suggesting that the tumor suppressor function for PLK3 cannot be generalized, but it depends on the context of the individual tumor type." (PMID 35053604, 2022).
breast carcinoma (5 papers, 2016 to 2025). "Additional studies reported overexpression of Plk3 to be significantly associated with adverse clinical outcome in ovarian and breast cancer." (PMID 27462786, 2016). "Reduced PLK3 expression has been observed in colon, lung, liver, and kidney cancer, while PLK3 upregulation has been noted in ovarian and breast cancer, indicating a poor prognosis and short survival." (PMID 39866232, 2025). "PLK3 has been previously identified as a novel independent prognostic marker for breast cancer, indicating a role of this isoform in disease progression." (PMID 38186570, 2023). "Specifically, in breast cancer, emerging biomarkers such as polo-like kinase (PLK) PLK 2, PLK3, and PLK5 have been validated as significant prognostic indicators through survival analysis utilizing the Kaplan–Meier Plotter database." (PMID 39432619, 2024). "This study also reveals that SETDB1-mediated PLK3 K106/200 methylation not only serves as a key signal driving HIF1α stability and BCSC properties but also acts as a prognostic factor for metastatic breast cancer patients." (PMID 38520019, 2024). "Furthermore, its specificity for PLK3-K106me1 or -K200me1 was verified in MDA-MB-231 cells and a clinical breast cancer specimen." (PMID 38520019, 2024). "Considering the critical role of the SETDB1 in contacting and methylating PLK3 and then contributing to drug-resistance and metastasis in LINC00115-driven BCSC, we assessed the effects of TTD-IN treatment combined with LINC00115 antisense oligonucleotides (ASO) on breast cancer metastasis." (PMID 38520019, 2024).
cataract (4 papers, 2019 to 2023). Partial or complete opacity of the crystalline lens of one or both eyes that decreases visual acuity and eventually results in blindness. "Previously, we reported that Polo like kinase 3 (Plk3), which is involved in cell cycle progression and apoptosis, and ataxia telangiectasia mutated (Atm), which is upstream of Plk3, are involved in galactose-induced cataracts." (PMID 36149903, 2022). "In the present study, we examined the effects of Plk3 and Atm inhibitors on galactose-induced cataracts that had already formed, revealing that Atm inhibitors reduced lens opacity." (PMID 36149903, 2022). "As a result, cataracts induced by galactose-containing diets closely resembled those ex vivo and had increased Plk3 expression." (PMID 31882756, 2019). "The association between Plk3 and diabetes has already been reported in diabetes-related cataracts, but its mechanism and other studies have not been specifically reported." (PMID 37134105, 2023). "GW843682X, a Plk3 inhibitor, and KU55933 an Atm inhibitor, prevent galactose induction of cataracts ex vivo." (PMID 36149903, 2022). "Although no prior studies have reported a direct relationship between Plk3 and cataract, exhaustive gene expression analyses of the murine LEGSKO and Mip mutant cataract models revealed that Plk3 expression was increased in both models compared with WT34,35." (PMID 31882756, 2019). "Previous studies have demonstrated that Plk3 and Atm prevent rat galactose-induced cataracts, but did not evaluate whether these inhibitors could reverse the opacity once formed." (PMID 36149903, 2022).
lung carcinoma (4 papers, 2012 to 2021). "Higher mRNA expressions of PLK1/4 were significantly related to male patients with either of lung cancer subtype, and higher mRNA expression of PLK3 was apparently associated with female patients with lung adenocarcinoma." (PMID 34080290, 2021). "Of note, mutations of PLK3 coding sequences seem to be rare, at lease in lung cancers." (PMID 23210979, 2012). "The results in this study supported Wiest's findings that PLK3 expression was decreased in lung cancer." (PMID 34080290, 2021). "PLK3 was knocked out in the H1975 lung cancer cell line using CRISPR." (PMID 33514736, 2021). "In addition, global methylation survival analysis showed that prognostic value of PLK1/2/4 methylation kept a similar trend between two lung cancer subtypes, whereas prognostic value of PLK3 methylation showed different between subtypes." (PMID 34080290, 2021). "Wiest et al39 found that PLK3 expression is down‐regulated in a majority of lung carcinoma samples." (PMID 34080290, 2021). "However, the biological role of PLK3 in lung cancer is still limited." (PMID 34080290, 2021). "Global methylation survival analysis showed that prognostic value of PLK1/2/4 methylation remained the same significant trend between two lung cancer subtypes, whereas prognostic value of PLK3 methylation lacked consistency." (PMID 34080290, 2021).
ovarian carcinoma (4 papers, 2004 to 2023). A malignant neoplasm originating from the surface ovarian epithelium. "The role of PLK3 in ovarian cancer is of special interest for this review and will be discussed further below." (PMID 34065956, 2021). "In different types of ovarian carcinoma, PLK3 has been found to be overexpressed and to correlate with mitotic activity without being used, however, as a prognostic factor." (PMID 34065956, 2021). "A kinome-wide screening for modulators of the growth-inhibitory effect of cisplatin revealed that the inhibition of PLK3 sensitizes cultured ovarian cancer cells to chemotherapy." (PMID 34065956, 2021). "In the group of primary ovarian carcinomas, 39 out of 77 cases (50.6%) were PLK3 positive, usually with pronounced PLK3 expression along the infiltrative tumour margins." (PMID 14970859, 2004). "For PLK1 and PLK3 expression, statistical correlation analysis with several clinicopathological factors was performed including all cases of primary ovarian carcinoma (n=77)." (PMID 14970859, 2004). "The importance of PLK isoenzymes for mitosis in ovarian carcinoma is underlined by our finding that the expression of both PLK1 and PLK3 correlated with the mitotic activity." (PMID 14970859, 2004). "In this study, the expression of PLK1 and PLK3 was determined immunohistochemically in tissue specimen of normal ovaries (n=9), cystadenomas (n=17), borderline tumours (n=13) and ovarian carcinomas (n=77)." (PMID 14970859, 2004). "In addition, other studies have demonstrated that overexpression of PLK3 results in shortened survival time of patients with hepatocellular carcinoma, and PLK3 is upregulated in breast and ovarian cancers." (PMID 35053604, 2022). "The expression of PLK1 and PLK3 was elevated in a fraction of cystadenomas and was even higher in the group of primary ovarian carcinomas, whereas borderline tumours tended to express lower levels of PLK1 and PLK3 compared to other epithelial tumour entities of the ovary." (PMID 14970859, 2004). "In a subgroup of ovarian carcinomas (n=54) in which data on KI-67 expression were available, a significant positive correlation of PLK1/PLK3-positive tumours towards higher KI-67 indices in comparison to PLK1/PLK3-negative tumours was observed." (PMID 14970859, 2004). "In ovarian carcinomas, 26% of cases were PLK1 positive and 50.6% of cases were PLK3 positive." (PMID 14970859, 2004).
diabetes (3 papers, 2016 to 2023). "Collectively, STZ diabetes-induced stimulation causes mitochondrial translocation of Parkin which is initiated by the Plk3-mtROS-PINK1 signal pathway." (PMID 37134105, 2023). "In this regard, the identification of the role of Plk3 in diabetes is expected to be a new starting point in future diabetes research." (PMID 37134105, 2023). "We found that Plk3 as a novel key regulator of diabetes mellitus by increasing mitochondrial ROS and newly discovered that it is an early initiator regulating mitophagy." (PMID 37134105, 2023). "This study found that Plk3 protein levels were increased under diabetes-induced stress as STZ or ROS." (PMID 35300109, 2022). "At this time, natural COA water maintains the stabilization of pancreatic cells by directly or indirectly inhibiting Plk3 that is increased in this STZ diabetes-related stress." (PMID 35300109, 2022). "Therefore, in this study, we confirmed that natural COA water had a positive function in preventing the increase of mitochondrial ROS by inhibiting the increased Plk3 protein in the diabetes-induced environment." (PMID 35300109, 2022). "However, there are insufficient reports on the specific mechanism between diabetes and Plk3." (PMID 35300109, 2022). "FOXO3A, Plk3, Parkin, and PINK1 genes may be used in future precision medicine as biomarkers for diabetes." (PMID 37134105, 2023). "However, there was still no specific study on how Plk3 affects pancreatic beta-cells under diabetes-related stress and by what mechanism." (PMID 35300109, 2022).